MMP1 (matrix metallopeptidase 1)
Diseases named in the same sentence as MMP1 in open-access papers (continued):
Sharing a sentence is not in itself a finding about the gene and the disease.
cancer (601 papers, 1992 to 2026). A tumor composed of atypical neoplastic, often pleomorphic cells that invade other tissues. "The F_6 CCL19+ fibroblasts have been shown to interact with T-cells via CXCL12/CXCR4 and F_8 MMP1+ myofibroblasts (myoF) have recently been linked to an immunosuppressive neighborhood in cancer." (PMID 41438752, 2025). "Only Health ABC participants in the highest compared to the lowest quartiles of MMP1, Activin A, and OPN at baseline demonstrated significantly increased risk for cancer during follow-up with HR ≥ 1.4 for MMP1 and OPN." (PMID 39695064, 2025). "MMP-1 is also linked to cancer progression, with certain genetic variations associated with poor prognosis." (PMID 41281748, 2025). "Among MMP members, MMP-1, -2, -3, -9, and -13 have been exclusively associated with cancer metastasis." (PMID 39063556, 2024). "To investigate the putative association of KK-LC-1 and MMP1 with cancer stemness, we examined the expression of KK-LC-1 and MMP1 in various sorted population of cells." (PMID 37147285, 2023). "Dkk1 has regulatory functions in the wnt signaling pathway and metalloproteinase expression (Mmp-1, -2 and -9) and has been associated with a poor prognosis in several cancers." (PMID 37298091, 2023). "Among them, MMP1, overexpressed in many cancers, was recently identified as a novel diagnostic and prognostic biomarker in head and neck SCC (NHSCC)." (PMID 36983009, 2023). "Despite important physiological functions, clinical studies found associations between changes in MMP1 and various cancers." (PMID 36009438, 2022). "Collectively, these experimental results indicated that oncogenic MMP1 causes cancer cells to acquire chemo-resistance during chemotherapy." (PMID 35267540, 2022). "MMP1 encodes a member of matrix metalloproteinases, and was associated with cancer invasion and metastasis by activating PAR-1." (PMID 36474268, 2022). "One of the studied single-nucleotide polymorphisms (SNPs) in the MMP1 promoter region is rs1799750, which controls the transcriptional activity of MMP1, and was associated with the incidence and progression of several types of cancer." (PMID 36009438, 2022). "Overexpression levels of MMP-1 have been reported in various cancer tissues, where MMP-1 overexpression was associated with angiogenesis, lymph node metastasis, and poor prognosis in CRC." (PMID 35456495, 2022). "For instance, genetic polymorphisms of matrix metalloproteinase 1 (MMP-1) are associated with carcinoma invasiveness." (PMID 35804810, 2022). "The overexpression of the target MMP-1 is strongly associated with the activation of the MAPK pathway in a variety of cancer types." (PMID 33921173, 2021). "MMP1 is a member of the matrix metalloproteinase family which has been reported as a risk factor for cancer development." (PMID 33777129, 2021). "It has been shown that MMP1 is associated with initiating malignant tumor formation leading to aberrant regulation of cell proliferation." (PMID 34301206, 2021). "On the contrary, a blockade of cancer-linked soluble (MMP-1, -3, -7,-9) and membrane-bound (MMP-14) MMPs using a broadband MMP inhibitor partially reduced BM disruption events in highly invasive breast acini." (PMID 33921304, 2021). "MMPs are enzymes that degrade and remodel the ECM and have been linked to cancer cell invasion, metastasis and angiogenesis, with MMP-1, -2, -7, -9 and -13 expression shown to correlate with worse outcomes." (PMID 34885111, 2021). "MMP-1 overexpression has been associated with metastasis in numerous cancers, and DTX3L has been reported to protect DNA from oxidative stress." (PMID 34073779, 2021). "APN is required for 14-3-3σ-mediated MMP-1 expression, which its upregulation has been associated with enhanced cancer growth and metastasis." (PMID 33287252, 2020). "Six genes were found to be implicated in cancer etiology/progression/clinical outcomes with high degree of certainty: MMP1, DDX4, TRPM3, DPP6, KCNA1, and MUC17." (PMID 32625238, 2020).
cancer (continued). "Many downstream genes of STAT3 have been identified in human cancers, including genes associated with cell cycle (cyclin D1 and cMyc), apoptosis (Bcl2-xL and Mcl-1) and metastasis (MMP1 and MMP2)." (PMID 32161621, 2020). "We showed that loss of miR-202-3p in cancer cells with low metastatic propensity increases MMP-1 expression and grants them a brain invasive phenotype rendering these cells more prone to disseminate to the brain." (PMID 33002044, 2020). "Taken together, our results showed that induction of COX-2 and MMP1 in BC cancer cells was associated with loss of claudin-5 and VE-cadherin in the brain endothelial cells and increased trans-endothelial migration." (PMID 32645833, 2020). "The expression level of two enzymes linked to cancer cell invasion (matrix metalloproteinase (MMP)-1 and MMP-2) was measured in LDD-1819 treated breast carcinoma cells using qPCR." (PMID 31489353, 2019). "A recent meta-analysis study explored the association between MMP1 polymorphism and cancer susceptibility." (PMID 31244308, 2019). "Increased expression of MMPs such as MMP-1, -2, -3, -7, -9, -13, -14 are associated with cancer progression, i.e. poor prognosis, poor cancer cell differentiation, invasive cancer stage with low patient survival and metastatic spread to distant sites." (PMID 30881433, 2019). "A previous study demonstrated that the polymorphism MMP1 -1607 1G > 2G was significantly related to a remarkable increase in cancer risk." (PMID 31275410, 2019). "In conclusion, an association between the MMP1–1607 (1G>2G) polymorphism and cancer risks was detected in both Asians and Caucasians." (PMID 30627228, 2018). "This meta-analysis revealed that MMP1–1607 (1G>2G) polymorphism was significantly associated with elevated risk of cancers." (PMID 30627228, 2018). "We have retrieved literature through PubMed in order to search the evidence of association between the MMP1–1607 (1G>2G) polymorphism and cancer risks in GWAS results." (PMID 30627228, 2018). "The significant association between the variation of MMP1–1607 (1G>2G) with some cancer types has been reported by different meta-analyses." (PMID 30627228, 2018). "The gene polymorphism MMP1–1607 (1G>2G) or rs1799750 in the MMP1 promoter has been associated with increased susceptibility for various cancers." (PMID 30627228, 2018). "In the current meta-analysis of 77 articles with 21,327 cancer patients and 23,245 controls, the MMP1–1607 (1G>2G) polymorphism was a strong risk factor in various cancers." (PMID 30627228, 2018). "Although the matrix metalloproteinase-1 (MMP1) polymorphism MMP1–1607 (1G>2G) has been associated with susceptibility to various cancers, these findings are controversial." (PMID 30627228, 2018). "Since MMP-9 resulted the marker that better discriminated cancer from controls, this molecule was combined with MMP-1 and/or -7 with the intention of increasing its diagnostic performance." (PMID 29207990, 2017). "In our study, MMP1 was found to be a candidate pathogenic gene and enriched in the pathway in cancer." (PMID 27034707, 2016). "It is possible that the different derivatives of the MMP1 allele result in varying levels of transcription and expression of MMPs in the cellular environment, resulting in a greater susceptibility to cancer in patients with the 2G allele." (PMID 25664615, 2015). "MMP-1 alleles have also been associated with the presence and increasing severity of different cancer lines." (PMID 25664615, 2015). "This association was observed for MMP1 expression in cancer cells as well as in cancer associated stroma." (PMID 24972610, 2014). "In our study, we observed an association between CTC_EMT and MMP1 expression in both cancer cells as well as in cancer associated stroma." (PMID 24972610, 2014). "To date, most genetic epidemiology studies of MMP-1 gene variation in relation to cancers have focused on the −1607 1G/2G polymorphism." (PMID 24505369, 2014).
cancer (continued). "MMP-1 expression was associated with growth of small HCC in which well-differentiated cancer cells invade the portal tract and fibrous bands, and these fibrous tissues disappear upon participation of MMP-1." (PMID 24978432, 2014). "Functional studies showed that the MMP-1 promoter polymorphisms exert haplotype effects on MMP-1 promoter activity in cancer cells." (PMID 24505369, 2014). "MMP1, a major member of the MMPs family, has been implicated in the development of a variety of cancers because of its ability to degrade ECM." (PMID 23441173, 2013). "The expression level of the MMP1 gene can increase in various tumors, which has been associated with a poor prognosis in some types of cancers." (PMID 23441173, 2013). "Studies show that the 2G/2G MMP-1 polymorphism is linked to the aggressive phenotype and the process of metastasis formation in cancers." (PMID 23108733, 2013). "Because our evidence suggested an association between MMP1 gene polymorphisms and MMP1 levels, the discovery of causative unidentified polymorphisms will be important in elucidating the mechanism of MMP1 on cancer and atherosclerotic cardiovascular disease." (PMID 23497408, 2013). "The single nucleotide polymorphisms (SNPs) in matrix metalloproteinase 1(MMP-1)play important roles in some cancers." (PMID 22655095, 2012). "Increased MMP-1 expression has been associated with the incidence or invasiveness of various types of cancer, including colorectal, esophageal, pancreatic, gastric, breast, and malignant melanoma." (PMID 23217186, 2012). "Seventeen studies investigating MMP1 (−1607) 1G/2G and its association with cancer metastasis were identified." (PMID 22348060, 2012). "In particular, the paper of Boström and colleagues sheds further light on these relationships, demonstrating significant differences of MMP-1 expression by cancer-associated stromal cells in luminal A, luminal B and triple-negative BC subclasses." (PMID 21834986, 2011). "For example, MMP1 is an invasion-promoting factor, and its up-regulation, as observed in our data, is associated with the invasiveness of the cancer." (PMID 21060876, 2010). "Although previous studies have documented a strong association between the 2G polymorphism in the MMP-1 promoter and the occurrence of several common cancers, including CRC, we were unable to corroborate these findings." (PMID 17311017, 2007). "It has been documented that the 2G type SNP of MMP-1 confers increased susceptibility to colorectal, ovarian, lung, endometrial, renal cell and head and neck cancers; and the 5A type SNP of MMP-3 is associated with an increased susceptibility to breast cancer." (PMID 17919326, 2007). "The abnormal expression of MMP1 is a hallmark feature in many malignant tumors." (PMID 40394037, 2025). "Regarding MMP-1, the rs1799750 variant is located in the promoter region of the gene, coding tissue collagenase I. The mentioned polymorphism has been analyzed in the context of cancer and other diseases." (PMID 40724896, 2025). "The expression of both MMP-3 and MMP-1 has been linked with cancer invasion and metastasis." (PMID 36765641, 2023). "The expression of MMPs transcriptionally regulated by E-cadherin cleavage fragments (MMP-2,9, and 14) or harboring association with reflux-attributed cancer (MMP1) were upregulated by acidified pepsin 24 h following 15 min stimulation; induction was rescued by alginate but not the placebo." (PMID 37175640, 2023). "MMP-1 was linked to several diseases, including lung emphysema, arthritis, and especially cancer." (PMID 37513440, 2023). "We further analyzed the effect of MMP1 mutation on the prognosis and survival of cancer patients." (PMID 36727076, 2022).
cancer (continued). "MMP1 is suggested as a potential prognostic factor for the malignancy risk of cancer, as it is activated and overexpressed by many signaling pathways involved in the initiation and progression of cancer, which can promote the hallmarks of cancer such as angiogenesis, metastasis, and invasion." (PMID 35267540, 2022). "Here, we analyzed the correlation between MMP1 and clinical manifestations of different cancers from the aspects of differential gene expression, survival prognosis of cancer patients, gene mutation and tumorigenesis correlation, immune infiltration correlation, and gene-related cellular pathways." (PMID 36727076, 2022). "A recent retrospective study has shown that salivary MMP-1 may serve as a promising diagnostic marker in oral squamous cell carcinoma, including cancer in the oropharynx." (PMID 36430813, 2022). "MMP1-1607 1G>2G polymorphism may have impacts on the susceptibility to cancer risk by modulating MMP1 expression levels." (PMID 31244308, 2019). "Therefore, we conducted this meta-analysis to further explore the association between MMP1–1607 (1G>2G) polymorphism and cancer susceptibility." (PMID 30627228, 2018). "The association between the MMP1–1607 (1G>2G) polymorphism and cancer risks was seen in the allele model (2G vs. 1G, OR: 1.174, 95% CI: 1.107–1.244), the dominant model (2G2G/1G2G vs. 1G1G, OR: 1.192, 95% CI: 1.090–1.303), and the recessive model (2G2G vs. 1G2G/1G1G, OR: 1.231, 95% CI: 1.141–1.329)." (PMID 30627228, 2018). "Therefore, we conducted this meta-analysis to explore the association between MMP1–1607 (1G>2G) and cancer risk." (PMID 30627228, 2018). "Mmp2, along with Mmp1, are the only genes in the fly genome encoding matrix metalloproteinase and are crucial for extracellular matrix homeostasis during normal development, wound repair, and cancer metastasis." (PMID 29256860, 2017). "Polymorphisms in promoter regions of MMP genes might be related to the susceptibility of digestive cancers, with a role in cancer development for MMP1 and MMP7, and a role of protection against cancer for MMP2 and MMP9." (PMID 25596746, 2015). "Similarly to MMP1, its common variants have received most research attention in association with cardiovascular disease, and a number of cancers." (PMID 25111588, 2015). "Furthermore, MMP-1 −519 A/G polymorphism displayed poor cellular differentiation (P = 0.024, OR = 3.8, CI = 1.69–8.56) attributing a higher risk of cancer progression." (PMID 24505369, 2014). "MMP1 overexpression tended to be associated with a higher risk of progression in ovarian serous papillary carcinomas and is possible chemoresistance marker in this cancer." (PMID 24804215, 2014). "Our investigations demonstrate that polymorphisms in the promoter regions of MMP1, 3, 7 and 9 might be associated with metastasis in some cancers." (PMID 22348060, 2012). "MMP1 is implicated in cancer susceptibility and metastasis in a variety of cancers." (PMID 22348060, 2012). "Indeed, it is known that MMP-1 polymorphisms are associated with diseases such as cancer in other ethnic groups." (PMID 22992122, 2012). "The findings from this study position us favorably to ask whether known cancer risk cofactors, namely, cigarette smoking and genetic predisposition, enhance MMP-1 activation in combination with DEP exposure." (PMID 19337515, 2009). "Thus, the presence of the MMP1 polymorphism has been associated with an increased risk of developing different human cancers including colorectal, renal and head and neck." (PMID 19094243, 2008). "Thus, the 2G allele of MMP1 has significantly higher transcriptional activity than the 1G allele and has been associated with an increased risk of common cancers, including oral, colorectal, renal and head and neck." (PMID 19094243, 2008).
cancer (continued). "In pan-cancer, based on the Connectivity Map (Cmap) database, we used the eXtreme Sum (XSum) algorithm to predict potential small molecules and drugs that could correct the detrimental biological effects caused by the dysregulated expression of MMP1." (PMID 40394037, 2025). "Therefore, further studies are required to promulgate the real functions by which the MMP1–1607 (1G>2G) polymorphism may influence cancer susceptibility and progression." (PMID 30627228, 2018). "However patients carrying combination of AG and GG genotype of MMP-1.2 polymorphism were significantly distributed among histological subtypes of cancer and showed significantly greater risk for poorly differentiated (PD) carcinomas (p = 0.001, OR = 3.803, CI = 1.69–8.56)." (PMID 24505369, 2014). "The MMP7-expressing cancer cells frequently co-expressed MMP1, MMP14, and several Wnt-related genes, consistent with a cancer cell type at high risk of malignancy and metastasis." (PMID 42079046, 2026). "Subsequent machine learning algorithms and cross-cancer analysis consistently identified Matrix Metalloproteinase-1 (MMP1) as a critical hub gene." (PMID 41828365, 2026). "Bioinformatics analyses further explored MMP1 expression and its clinical relevance across different cancer types." (PMID 40287412, 2025). "The C-statistic for cancer increased little, from 0.61 to 0.64 by the addition of 4 biomarkers, MMP1, Activin A, TRAIL, and uPAR." (PMID 39695064, 2025). "In summary, this research highlights the critical role of MMP1 in preserving the pancreatic ductal characteristics of cancer cells." (PMID 40092486, 2025). "The expression patterns of genes associated with high-risk signatures, namely MMP1, MMP12, and TIMP1, indicate their presence in a subset of macrophages, endothelial cells, and cancer-associated fibroblasts (CAFs)." (PMID 40362553, 2025). "In our study, we have discovered a distinct MMP1+ cell subset that serves as a transitional bridge between normal pancreatic cells and cancer cells." (PMID 40092486, 2025). "Apart from this, the reduction in matrix metalloproteinase-1 (MMP-1) levels mediated by GLP-1RA attenuates the proliferative capacity of cancer cells." (PMID 40140925, 2025). "The matrix metalloproteinase family, including MMP1, MMP2, and MMP9, causes cancer cell invasion and migration during cancer progression." (PMID 40093316, 2025). "Further pan-cancer ST and scRNA-seq data demonstrated that MMP1 expression was predominantly localized in malignant cells." (PMID 40394037, 2025). "In the pathological processes of these cancers, MMP1 shows abnormally high expression levels regulated by upstream genes and pathways." (PMID 40666104, 2025). "The top five upregulated genes (MMP1, COL10A1, CXCL8, TM4SF1 and PLAU) have been associated with cancer progression and metastasis-inducing mechanisms." (PMID 40640495, 2025). "MMP-1 creates a microenvironment within tissues that are involved in the growth and invasion of cancer cells, and the overexpression of MMP-1 is also involved in carcinogenesis." (PMID 40094840, 2025). "Pan-cancer analysis of MMP1 indicated that it is highly expressed in most tumors compared to normal tissues." (PMID 41425594, 2025). "We first identified the crucial role of MMP1 in the transition from normal pancreatic cells to cancer cells." (PMID 40092486, 2025). "The findings revealed that the knockdown of MMP1 significantly reduced the migration and invasion capacities of these cancer cells." (PMID 41425594, 2025). "To further investigate the prognostic impact of MMP1 in tumors, we conducted a differential expression analysis comparing high and low MMP1 expression groups across pan-cancer datasets." (PMID 40394037, 2025). "The second, F6: inflammatory myofibroblasts (IL11+MMP1+CXCL8+IL7R+), characterizes early human skin wounds, inflammatory diseases with scarring risk and cancer." (PMID 40993240, 2025).